ZNF550 (zinc finger protein 550)
Description:
May be involved in transcriptional regulation.
Synonyms: MGC41917
Tractability: PROTAC: ubiquitination databases record sites on it.
Gene: Protein-coding gene on chromosome 19 (57,535,257 to 57,559,863, reverse strand). Ensembl gene ENSG00000251369.
Subcellular location: Nucleus
Subcellular location (Human Protein Atlas): Vesicles; Microtubules
Pathways (Reactome):
Gene expression (Transcription): Generic Transcription Pathway
Gene Ontology:
Molecular function: protein binding; DNA-binding transcription factor activity, RNA polymerase II-specific; RNA polymerase II transcription regulatory region sequence-specific DNA binding
Biological process: regulation of transcription by RNA polymerase II; negative regulation of DNA-templated transcription; regulation of DNA-templated transcription
Cellular component: nucleus
Genetic constraint (gnomAD): Loss-of-function variants: 41 observed, 39.61 expected, observed/expected ratio (o/e) 1.04, 90% interval 0.81 to 1.34. The upper end of that interval is the gene's LOEUF score, 1.34, which puts it in group 5 of 6, group 1 being the genes least tolerant of losing a copy. Missense variants: 548 observed, 543.67 expected, observed/expected ratio (o/e) 1.01, 90% interval 0.94 to 1.08. Synonymous variants: 223 observed, 207.91 expected, observed/expected ratio (o/e) 1.07, 90% interval 0.96 to 1.2.
Homologues: Orthologues: chimpanzee ZNF550 (99% identical), macaque ZNF550 (95% identical), pig ZNF550 (76% identical), dog ZNF550 (74% identical), rabbit ZNF550 (70% identical), guinea pig ZNF550 (68% identical), Drosophila melanogaster CG3281 (24% identical), Drosophila melanogaster CG2712 (23% identical), Drosophila melanogaster Phs (22% identical). Paralogues in human: ZNF599 (61% identical), ZNF805 (57% identical), ZNF264 (56% identical), ZNF266 (40% identical), ZNF582 (39% identical), ZNF404 (38% identical), ZFP90 (38% identical), ZFP37 (37% identical), ZNF10 (37% identical), ZNF555 (37% identical), ZNF749 (37% identical), ZNF778 (37% identical), and 50 more.
Diseases named in the same sentence as ZNF550 in open-access papers:
ZNF550 is named in the same sentence as 1 disease in open-access papers, as found by Europe PMC text mining. Sharing a sentence is not in itself a finding about the gene and the disease. The quoted sentences say what the papers report.
colon cancer (1 paper, 2021). "This included PPP1R14D, BST2 and ZNF550, whose expression was induced by 5-aza-2′-deoxycytidine (decitabine) treatment in colon cancer cell lines with low basal expression and high promoter methylation of these genes." (PMID 33892786, 2021).